TGM2 (transglutaminase 2)
Diseases named in the same sentence as TGM2 in open-access papers (continued):
Sharing a sentence is not in itself a finding about the gene and the disease.
neurodegenerative disease (35 papers, 2007 to 2025). A disorder of the central nervous system characterized by gradual and progressive loss of neural tissue and neurologic function. "In keeping with this, TGM2 has been linked to multiple neurodegenerative diseases, including AD, ALS, HD, LBD, MS, and PD, among others." (PMID 39769187, 2024). "The direct targeting of TGM2 activity for the treatment of various neurodegenerative diseases has been reviewed." (PMID 39769187, 2024). "Transglutaminase 2 (TG2) is implicated in PD, as well as in other neurodegenerative diseases characterized by protein misfolding." (PMID 36715870, 2023). "Other neurodegenerative diseases, including AD and PD, also show increased levels of TGM2." (PMID 36421678, 2022).
infection (27 papers, 2007 to 2025). The state of being infected such as from the introduction of a foreign agent such as serum, vaccine, antigenic substance or organism. "In children, the infection prompts the immune system to produce antibodies that can be detected in the serum, showing low serum IgG antibodies against transglutaminase-2." (PMID 41353374, 2025). "We detected TGM2 to be highly up-regulated (up 5.4-fold) after FIV infection, similar to previous findings for HIV." (PMID 24642186, 2014). "Finally, infection increases GFAT enzymatic activity by transglutaminase 2 (TG2)-dependent PTM on GFAT." (PMID 38159854, 2023). "We examined whether TGM2 might not only act downstream of TLR4 signaling but also act as an upstream activator of the TLR4 signal pathway in our infection model." (PMID 29321784, 2017). "The newly constructed hwp1Δ/Δ strain SCH1211 and the parental SC5314 were tested for virulence in wild type C57BL/6 and Tgm2-/- mice to determine whether TG activity participated in C. albicans tissue infection such as in the kidneys where TG2 is active." (PMID 24260489, 2013). "ALKBH5 knockdown increased the levels of the IL-1β, CSF3, TGM2, and SRC transcripts during infection by P. aeruginosa, C. diphtheriae, WT HSV-1, or the ICP34.5 mutant virus." (PMID 36625590, 2023). "RT-qPCR and Western blot analysis showed that the levels of IL-1β, IL-6, TNF-α, and iNOS increased and mRNA and protein levels of TGM2 decreased in liver tissues of HFD-fed mice in comparison to control mice, while opposite results were observed by the further infection of AAV8-anti-miR-9-5p." (PMID 35261562, 2021). "After infection of miR-9-5p into THP-1 macrophages, the expression of TGM2 was detected." (PMID 35261562, 2021). "At the peak of infection, when animals developed the most severe lesions, infected animals had higher levels of several gene transcripts involved in cellular proliferation and inflammation, including matrix metalloproteinase-7 (MMP7), transglutaminase-2 (TGM2), and oncostatin M (OSM)." (PMID 30696739, 2019).
cardiovascular diseases (13 papers, 2016 to 2024). "Induction of both interleukin 6 (IL6) and transglutaminase 2 (TG2) expression participates in human and experimental cardiovascular diseases." (PMID 38650935, 2024). "Furthermore, TGM2 is involved in age-related kidney and cardiovascular diseases and upregulated in vascular endothelial cells in gastrointestinal cancer, which is associated with poor patient survival via activating downstream NF-κB-dependent pathways." (PMID 36978029, 2023).
neurological disorders (7 papers, 2012 to 2024). "TGM2 inhibitors are the subject of intense investigation for their potential utility for CF and neurological diseases such as Huntington and Alzheimer diseases." (PMID 24434788, 2014). "In addition, CX3CR1 is a chemokine receptor expressed in microglia, as well as the mononuclear phagocyte system, it is unclear whether Tgm2 knockout in macrophages, monocytes or neutrophils will contribute to the pathogenesis of neurological diseases." (PMID 36878712, 2023). "Importantly, unlike compounds intended for use in neurological disorders, TGM2 inhibitors suitable for use in CF patients will not need to cross the blood-brain barrier." (PMID 24434788, 2014).
adenocarcinoma (5 papers, 2011 to 2024). A common cancer characterized by the presence of malignant glandular cells. "At 10 and 15 months AGI, TROP2-positive adenocarcinoma regions of Pten(i)pe−/− mice were TGM2 positive, whereas in PINs, only a subset of TROP2-positive cells expressed TGM2." (PMID 35867798, 2022). "In the GC sample cohort from the TCGA (Stomach adenocarcinoma (TCGA, Firehose Legacy, n = 478)), the levels of several markers for macrophages (FN1, MRS1, CD68, and CCL7), blood vessels (CDH5) and lymphatic vessels (VEGFC) exhibited positive correlations with TGM2 expression." (PMID 32467608, 2020).
connective tissue disease (5 papers, 2019 to 2025). "TGM2 can regulate several key profibrotic activities of TGF‐β suggesting that attenuating TGM2 function may be of benefit in severe forms of connective tissue disease with skin fibrosis." (PMID 39800950, 2025).
lymph node (5 papers, 2012 to 2023). "Univariate analyses indicated a significant association between OS and primary tumor site, T stage, cervical lymph node metastasis, TNM stage, TGM2 expression and BNIP3 expression in laryngeal SCC." (PMID 22458929, 2012).
metabolic disorders (5 papers, 2014 to 2025). "Matrix protein molecules such as Adipoq, Angptl4, Col4a4, Hrg, Tgfbi, Tgm2, Vcan and Vtn increase with age, and they may promote the occurrence of fatty liver during aging by affecting fat accumulation and metabolic disorders." (PMID 40537154, 2025).
inflammation (4 papers, 2013 to 2024). Aberrant reaction of the microcirculation characterized by movement of fluid and leukocytes from the blood into extravascular tissues. "In addition, Tgm2-deficiency resulted in impaired inflammatory responses in a Th17-mediated airway inflammation model, and impaired antigen-specific antibody production." (PMID 32793209, 2020).
heart disease (3 papers, 2018 to 2023). "RNA sequencing analysis reveals Tgm2 and Ace1, two genes with well-established links to cardiac repair, as potential targets of RA signaling in primary cardiomyocytes, thereby providing novel links between the RA pathway and heart disease." (PMID 34623260, 2021). "Importantly, some of the identified RA-responsive genes, such as transglutaminase 2 (Tgm2) and angiotensin converting enzyme (Ace1), have well characterized roles in cardiac repair, thereby providing new molecular links between RA signaling and heart disease." (PMID 34623260, 2021).
brain diseases (2 papers, 2022 to 2023). "Challenges ahead will be to investigate the roles and function of TGM1, TGM2, ATF3, RCN3, ORAI1, and ITPR3 in TBI as well as TBI-induced secondary brain disorders." (PMID 37645012, 2023).
hematological disease (2 papers, 2021 to 2022). "TGM2 is associated with 329 diseases, including immune system, endocrine, metabolic, cardiovascular, epidermal, renal and hematological diseases." (PMID 33422029, 2021).
TGM2 also shares sentences with these, for which no sentence is quoted: inflammatory bowel disease (15 papers); Parkinson disease (15); autoimmune thyroiditis (12); multiple sclerosis (12); metastatic disease (10); rheumatoid arthritis (10); Atrophy (9); heart failure (8); autoimmune liver disease (7); Sepsis (7); amyotrophic lateral sclerosis (6); autoimmune enteropathy (5); COVID-19 (5); Hashimoto thyroiditis (5); Hepatic steatosis (5); myocardial hypertrophy (5); thyroid (5); cataract (4); duodenitis (4); Hepatitis (4); idiopathic pulmonary fibrosis (4); pancreatic adenocarcinoma (4); pulmonary hypertension (4); renal disease (4); skin cancer (4); Ureteral obstruction (4); Allergy (3); atopic dermatitis (3); autoimmune gastritis (3); bladder cancer (3).
A further 242 diseases each share a sentence with TGM2 in 3 papers or fewer.